CRP (C-reactive protein)
Diseases named in the same sentence as CRP in open-access papers (continued):
Sharing a sentence is not in itself a finding about the gene and the disease.
infection (continued). "Our study further confirmed the predictive role of CRP on the occurrence of independent POP infection rather than postoperative overall infection symptoms in elderly patients with hip fractures, with its contribution value to the prediction model ranked first." (PMID 38816811, 2024). "By the seventh postoperative day, follow-up tests showed that the white blood cell count and CRP levels had returned to normal, indicating a good postoperative recovery with no signs of infection." (PMID 39659804, 2024). "This can be adjusted for by measuring the acute phase proteins, C-reactive protein (CRP) and α-1-acid glycoprotein (AGP), alongside plasma zinc concentration and either excluding observations where infection is concurrent for population studies or applying a correction factor to individual values." (PMID 37032778, 2023). "In the studied group of patients, no changes in CRP levels were noted, and infections were ruled out by clinical assessment and blood tests." (PMID 36983411, 2023). "Next, we investigated how the discriminative power of CRP changes in more severe disease and whether NLR can assist the identification of patients with infection in certain severity categories." (PMID 37761321, 2023). "In addition, neither the ETEC challenge nor the intervention approaches used in this study induced an APP response of haptoglobin, CRP, and MAP, which is generally triggered as a result of infection by pathogens." (PMID 38143275, 2023). "CRP is a non-specific acute-phase protein and a sensitive biomarker of inflammation, infection, and tissue damage." (PMID 37510958, 2023). "After multiple examinations, the patient's blood routine, C-reactive protein, blood culture, and CT examination showed no signs of infection, and even the culture from the end of the central venous catheter showed no pathogen growth." (PMID 36713573, 2023). "Moreover, the clinical liver function index (TBIL, ALT, AST, ALP, and γ-glutamyl transpeptidase (GGT)), infection index (e.g., PCT), and inflammation index (e.g., WBC and CRP) were positively correlated." (PMID 37660138, 2023). "This is illustrated by a recent meta-analysis that found that in a hypothetical cohort of 1000 neonates, assessing serum CRP level alone would miss 152 cases of infection (false-negative result) and wrongly diagnose 156 cases (false-positive result)." (PMID 37371798, 2023). "Only 2 out of 22 patients diagnosed with a SII had a CRP > 10 mg/L (9%), resulting in a low negative predictive value to exclude infection." (PMID 36282416, 2023). "While undergoing repeated surgical interventions including a removal of osteosynthesis material and total endoprosthesis of his right hip including double subtrochanteric osteotomy, the patient developed drastically increasing infection parameters of PCT and CRP." (PMID 37064073, 2023). "Biomarkers, such as C-reactive protein (CRP), procalcitonin (PCT), white blood cell count and erythrocyte sedimentation rate, can serve as useful adjunctive tools in combination with clinical symptoms and signs in the diagnosis of infection." (PMID 36830264, 2023). "In CN, WBC count, C-reactive protein (CRP), and ESR may be normal, but these markers are almost always elevated to some extent in the setting of infection." (PMID 37788033, 2023). "Therefore, abnormal CRP elevation immediately after PD should be considered uncontrolled inflammation, such as the coexistence of POPF and infection or drainage failure." (PMID 37964345, 2023). "The CRP and NLR ratio is statistically higher in infection, which originates from permanent teeth." (PMID 36981782, 2023). "CRP synthesis under CRP-apheresis is not impaired, and the liver can react normally to potential infections." (PMID 37626775, 2023).
infection (continued). "Commonly used diagnostic biomarkers in clinical laboratories including C-reactive protein (CRP) and Procalcitonin (PCT) were not statistically different between groups of B1, B2, C1, and C2 on the 7th day and 48 h after infection, respectively." (PMID 37612659, 2023). "Excluding these subjects, as well as subjects with increased CRP levels (>10 mg/L), indicating an ongoing infection/other non-healthy state, showed that the CRP level did not change over time." (PMID 37571403, 2023). "In all these previous studies IL-6 or CRP were not measured during infection, but at a fixed timepoint during pregnancy." (PMID 37789021, 2023). "When we included the coinfection with H. pylori in the analysis, we observed that hepcidin and AGP remained associated with EBV infection irrespective of H. pylori infection, while CRP seemed dependent on infection with both pathogens." (PMID 36675141, 2023). "Our patients showed high levels of ASO titer, inflammatory cytokines, and neuropsychological tests scores in the absence of an ongoing infection and with negative routine infection/inflammatory markers (CRP and ESR)." (PMID 38239595, 2023). "One of the most promising outcomes of phage treatment might be a decrease in C reactive protein (CRP) values, leukocyte counts, and erythrocyte sedimentation rates (ESR), as well as an impact on the inflammatory response to infection." (PMID 37893232, 2023). "In the absence of infection, the peak postoperative CRP value is assumed to reflect the extent of tissue damage." (PMID 37038129, 2023). "We compared the postoperative infection indicators between the two groups and showed that localized saline irrigation of spinal TB lesions with streptomycin was effective in reducing ESR and CRP levels at 1 week postoperatively (both p values < 0.05)." (PMID 37563683, 2023). "C-reactive protein (CRP) is a nonspecific acute-phase reactant that has elevated levels when a patient has infection or inflammation." (PMID 37623485, 2023). "ROC curve analysis of baseline CRP (cutoff 49.5mg/dl), size of WON (cutoff 127mm) and CTSI (cutoff of 9) showed AUROC (area under ROC) of 1, 0.97, and 0.81 respectively for the future development of infection in WON." (PMID 36895535, 2023). "In addition, clinical markers such as lipid and liver enzymes profiles, Cr, FBS, CRP, ESR, uric acid, 25-hydroxyvitamin D, and real-time PCR Ct values were correlated with infection mortality." (PMID 37323564, 2023). "hBD2 showed significant diagnostic accuracy in patients with an infection, in contrast to PCT and CRP which, in our study, failed to discriminate an infectious from non-infectious origin of inflammation." (PMID 37296737, 2023). "The predictive performance of PCT for infection was similar to that of ferritin, WBC, and CRP." (PMID 36752185, 2023). "C-reactive protein (CRP) is known to be an acute phase reactant, a glycoprotein produced by the liver and released into the blood stream within a few hours of a tissue injury occurring, at the start of an infection, or due to other sources of inflammation." (PMID 36662693, 2023). "When compared with 442 alive at discharge with no baseline infection not taking rifaximin, we found substantial differences in baseline HE, creatinine, and CRP, but 6-month mortality was similar." (PMID 35970815, 2023). "Contrarily, the incidence rates of anti‐SSA/Ro60‐positive and hypergammaglobulinemia were much higher, while CRP was slightly higher in H. pylori‐positive infection compared to H. pylori‐negative pSS patients." (PMID 37904694, 2023). "Some biomarkers such as PCT, CRP, SAA, and ESR are helpful in the identification of infection, yet remain unclear for AAV patients." (PMID 36653805, 2023). "Because CRP was frequently tested in situations of fever, illness and infection, a large proportion of patients presenting as afebrile and in good health would not receive CRP testing." (PMID 35781808, 2023).
infection (continued). "Serum CRP protein is almost absent in healthy people but can increase a thousand-fold when tissue is damaged during infection, tissue trauma, or inflammation." (PMID 36670722, 2023). "The morphology of blood cells and the CRP protein level (0.04–0.33 mg/dL) remained within the normal range and did not indicate an ongoing infection in any of the included patients." (PMID 36983411, 2023). "Hence, the pooled analysis of CRP and TNF-α was conducted utilizing the random effect model, whereas the pooled analysis of infection-related complications was carried out through the use of the fixed-effect model." (PMID 37566134, 2023). "Looking at other commonly used infection markers, the white blood cell counts and C-reactive protein (CRP) values did not demonstrate any significant differences between cohorts." (PMID 37107071, 2023). "The C-reactive protein is a sensitive and non-specific marker for inflammation which can be used to assess the severity of an inflammation and to predict if an infection can be expected to be self-limiting or severe." (PMID 37324137, 2023). "CRP levels do not significantly rise during the early stages of infection but increase with disease progression." (PMID 37510151, 2023). "ESR and CRP are non-specific markers of inflammation that are elevated in SLE and are associated with organ inflammation and infection, respectively." (PMID 38505536, 2023). "Using the same procedure, PCT and CRP failed to effectively classify the inflammation regarding the presence of infection." (PMID 37296737, 2023). "Despite the fact that not all patients showed signs of infection, the blood parameters of systemic inflammation were elevated (leukocytes/mm3, total neutrophils and C-reactive protein)." (PMID 37887202, 2023). "Serum CRP protein is almost absent in healthy individuals but increases up to 1000-fold when tissue damage occurs during infection, tissue trauma, and inflammation." (PMID 36670722, 2023). "It is possible that some cases assigned to the high hs-CRP class have an active infection rather than chronic inflammation during sample collection." (PMID 37388285, 2023). "CRP level and WBC count have been used as early biomarkers of infection." (PMID 36650580, 2023). "Most hospitals in the UK National Health Service (NHS) use a blood test called C-reactive protein (CRP) to monitor response to infection, but it is not specific for bacterial infection and shows a delayed response." (PMID 37254156, 2023). "Before surgery, C reactive protein and erythrocyte sedimentation rates were analyzed for every patient, to rule out the presence of active infection." (PMID 36902607, 2023). "CRP is a nonspecific protein produced by the liver in response to inflammation, infection, and tissue damage." (PMID 36717689, 2023). "The cut-off CRP and PCT values used in that study were slightly lower than those found in the present study, which might be due to the higher rate of infection in the current study cohort." (PMID 37876167, 2023). "Neutrophil percentage, leukocyte count, and CRP in patients with DKA were raised compared to those without infection." (PMID 37510185, 2023). "Daily CRP monitoring and the recognition of the CRP kinetics could be useful in the prediction of ICU-acquired infections." (PMID 37834754, 2023). "The daily CRP values had a significant increase in the 48-h period preceding the diagnosis of infection, whereas non-infected patients exhibited relatively stable CRP levels." (PMID 37834754, 2023). "The findings from this study indicate that the changes in CRP and ESR levels were significant from the moment the infection was confirmed through to the successful treatment of the infection and into the post-revision period.One of the controversial issues is culture-negative PJI." (PMID 37637597, 2023). "The higher-than-normal CRP value without ongoing infection, as well as the elevated blood urea nitrogen and creatinine levels, significantly influenced the results." (PMID 37370833, 2023).
infection (continued). "It integrates the circulating levels of three immune proteins that change their expression differentially in response to an acute infection: the tumor necrosis factor-related apoptosis inducing ligand (TRAIL), the interferon-gamma induced protein-10 (IP-10), and CRP." (PMID 37239167, 2023). "CRP is a non-specific acute-phase protein that is elevated in plasma in response to infection, inflammation, tissue damage, and malignancy." (PMID 37108132, 2023). "CRP is a non-specific acute phase protein, induced by IL-6 in the liver, and is a sensitive biomarker of inflammation, infection, and tissue damage." (PMID 37373750, 2023). "Although, the aim of the current study was not to identify biomarkers, the concomitant increase in LCN2, CRP and IL6, that we found in this study, might aid in recognizing preterm infants experiencing infection." (PMID 37496672, 2023). "Although levels of acute-phase proteins (APPs) can be expected to be elevated in the early phases of infection (i.e., mild and moderate cases) and slowly wane with chronic infection (i.e., severe cases of CS), serum levels of SAA and CRP were increased in the positive control group in our study." (PMID 37964301, 2023). "ORs were noticeably higher in predicting infection with the combined use of CRP and NLR than with CRP or NLR alone in both univariate and multivariate analyses (adjusted for age, sex, dialysis vintage, DM status, vascular access type, Kt/V, comorbidity index, underlying kidney disease and smoking)." (PMID 37016028, 2023). "CRP blood levels are today widely used as a non-specific but clinically useful marker for infection." (PMID 37868984, 2023). "The results of this experimental study showed that NE infection exerted long-term effects on broiler chickens, including reduced intestinal barrier function 7 d after infection, continued high levels of MPO and CRP in the serum, and inferior growth performance compared to those in the NC group." (PMID 37143114, 2023). "Patient inflammatory markers including CRP, ESR, and WBC are often raised in response to infection." (PMID 37303456, 2023). "In the present study, 16% of patients after HIPEC with mitomycinC/doxorubicin underwent a CT scan due to increased CRP levels without diagnosing any postoperative infection." (PMID 36631814, 2023). "Follow-up examinations showed a decrease in infection markers such as WBC, CRP, and PCT." (PMID 38129781, 2023). "Inflammatory biomarkers such as WBC, Neutrophils, CRP, IL-6, PCT and ESR could be used to distinguish between non-infection and mild infection, indicate severity of foot ulcer infection and monitor response of anti-infective therapy." (PMID 37065766, 2023). "Our study population was highly selected since the subjects had failed on corticosteroids and that IL-6-blocking regimens such as TCZ were considered inappropriate due to a lack of CRP reaction in case of an infection." (PMID 37304255, 2023). "CRP-levels were high in both TB-groups and significantly increased compared to endemic control, whereas remaining TB-negative groups showed negative-to-low levels of CRP indicating that they had no ongoing infection." (PMID 37386541, 2023). "Studies did not report on adverse effects, other than two studies showing no overall effect on inflammation or infection in children 2–11 years of age as measured by C-reactive protein (CRP) (MD = 0.04)." (PMID 37688369, 2023). "Though 17 children had 10-year hs-CRP > 10 mg/L, none met our definition of active infection by also having a white blood cell count >10 K/ul (blood samples collected at time of research visit rather than during a doctor's visit due to episode of illness)." (PMID 37388285, 2023). "The reason for this is the secondary peak of CRP between days 5 and 8, also present in absence of any infection." (PMID 36631814, 2023). "Although the C-reactive protein (CRP) test is non-specific, it is very useful in the characterization of acute inflammation and infection." (PMID 37461754, 2023).
infection (continued). "The median serum CRP level of patients diagnosed with a SII was 2.1 mg/L (range: 0.3–28) versus 2.3 mg/L (range 0.4–6.0) for those without an infection (P = 0.778)." (PMID 36282416, 2023). "Furthermore, in our experiment, inflammation-related indicators in blood, such as WBC, CRP, IL-6, IL-1β and TNF-α, exhibited varying degrees of elevation since 18 h of infection." (PMID 37587524, 2023). "There were no signs of infection, including inflammatory index (CRP) curve, blood cultures, chest X‐ray and pharyngeal swab." (PMID 37644805, 2023). "First, the laboratory blood test variables in the MIMIC database do not represent all commonly used infection-related parameters; for example, procalcitonin and C-reactive protein are not reported in the MIMIC database." (PMID 37817106, 2023). "Still, irrespective of the presence of concomitant infection, systemic autoimmune disease or the presence of atherosclerotic burden, CRP elevation was predictive of the SHS." (PMID 37119383, 2023). "As CRP elevation was similar between groups, it is not likely that differences in postoperative inflammatory stress or infection explain the improvement in metabolic control in the isCGM group." (PMID 37540239, 2023). "Monocyte distribution width is a new biomarker for infection and has shown to be at least equivalent to procalcitonin and CRP, if not superior." (PMID 37764075, 2023). "For LRTIs in ambulatory care, the robustness and accuracy of CRP to rule out severe infections are high." (PMID 37324137, 2023). "They reported that 80 mg/L CRP is recommended to rule in serious infections, and 20 mg/L CRP is necessary to rule out serious infections." (PMID 37510151, 2023). "Moreover, RIPK3 in the serum positively correlated with circulating infection and inflammatory indicators (PCT and CRP)." (PMID 37475188, 2023). "Evaluation of inflammatory markers such as C-reactive protein (CRP) can help clinicians distinguish non-severe infections from more severe infections in patients with relatively nonspecific LRTI symptoms such as a cough or shortness of breath." (PMID 36673130, 2023). "Levels of CRP that remain normal in repeated measurements indicate the absence of infection with a high specificity." (PMID 36978375, 2023). "This study using a large dataset demonstrated that the concurrent examination of CRP and IL-6 or PCT could be helpful for the early suspicion of infection, but careful interpretation is important because of their discrepancies." (PMID 36555941, 2022). "And the serum levels of CRP and PCT increase apparently in response to infection or tissue injury, the degree of increase was significantly correlated with the severity of infection, and the ALB level may exist decrease during the response to acute infections." (PMID 35479953, 2022). "The CRP levels were compared between patients with postoperative infection and patients without postoperative infections using independent samples t-test." (PMID 35350520, 2022). "Several studies have identified that airway damage and acute exacerbations of infection are the main reasons for the poor prognosis for CPFE, which could lead to an increase in CRP, consistent with our results." (PMID 36038872, 2022). "Moreover, age does not increase the laboratory parameters that usually reflect the severity of infections, such as WBC, CRP, and ESR." (PMID 35628858, 2022). "The acute-phase CRP, also known as high-sensitive CRP, is a non-specific biomarker of inflammation rapidly produced in the liver in response to tissue injury or infection." (PMID 36699006, 2022). "The median CRP and PCT levels of the infections group were 5.65 mg/dL and 1.5 ng/mL respectively, and those without infections had a significantly lower median CRP of 3.03 mg/dL and median PCT of 0.7 ng/mL (p = 0.002 and p < 0.001, respectively)." (PMID 36143057, 2022). "The infection in patient 4 was detected by elevated C-reactive protein levels without fever or pelvic pain." (PMID 34964075, 2022).